USP33 (ubiquitin specific peptidase 33)
Diseases named in the same sentence as USP33 in open-access papers (continued):
Sharing a sentence is not in itself a finding about the gene and the disease.
glioma (4 papers, 2024 to 2025). A benign or malignant brain and spinal cord tumor that arises from glial cells (astrocytes, oligodendrocytes, ependymal cells). "In vitro studies have suggested that the overexpression of USP33 can significantly inhibit the migratory ability of glioma cells." (PMID 40149733, 2025). "Mechanistically, USP33 inhibits the migration of glioma cells by regulating the function of the Slit/Robo signaling pathway." (PMID 40149733, 2025). "USP33 protein synthesis is primarily induced in glioma stem cells by hypoxia." (PMID 41009560, 2025). "For instance, USP33 deubiquitinates and stabilizes HIF-2α, promoting the hypoxia response in glioma stem cells, and its elevated expression accelerates ovarian cancer progression by stabilizing CBX2." (PMID 40695806, 2025). "USP33 deubiquitinates and stabilises HIF-2α in glioma cells, aiding glioma stem cell maintenance, tumour vascularization, and glioblastoma growth." (PMID 39584532, 2024). "Additionally, USP33 is preferentially induced in glioma stem cells by hypoxia, although no change in USP33 transcription is observed in response to hypoxia." (PMID 40695806, 2025).
gastric cancer (3 papers, 2019 to 2022). A primary or metastatic malignant neoplasm involving the stomach. "Slit2, Robo1 and USP33 expressions were analysed in datasets obtained from the Oncomine database and measured in human gastric cancer specimens." (PMID 30896071, 2019). "USP33 stabilizes Robo1 by reducing the ubiquitination of Robo1, thus is required for the Slit2‐Robo1 signalling in inhibiting gastric cancer cell migration and EMT." (PMID 30896071, 2019). "Similarly diverse roles of USP33 in deubiquitinating Parkin gene, HERC2, centrosome biogenesis, tumor progression of gastric carcinoma as well as DENV neuropathogenesis are well established." (PMID 33936086, 2021).
pancreatic cancer (3 papers, 2023 to 2025). "In conclusion, our study found that USP33 contributed to the proliferation and metastasis of pancreatic cancer through a positive feedback loop with TGF-β signaling pathway." (PMID 37322017, 2023). "In our research, we reported for the first time that USP33 mediated the proliferation and metastasis of pancreatic cancer through its deubiquitinating function which may provide a novel explanation for PC malignant development." (PMID 37322017, 2023). "USP33 is also reported to enhance the protein stability of transforming growth factor beta receptor 2 (TGFBR2) by removing the K63-linked ubiquitin chains on TGFBR2, thereby enhancing transforming growth factor-beta (TGF-beta) signaling and promoting pancreatic cancer cell migration and invasion." (PMID 40695806, 2025). "In the FIGHT-101 clinical trial, one of five patients with pancreatic cancer showed a partial response to anti-FGFR1-3 treatment (pemigatinib); this case was positive for FGFR2::USP33 fusion." (PMID 38542259, 2024). "Though there have been numbers of reports discussing the role of USP33 in cancers, the function of USP33 in pancreatic cancer has not been clearly elucidated." (PMID 37322017, 2023). "Though it had been reported that USP33 participated in regulation of malignant phenotype of different tumors, there were no research demonstrating the role of USP33 in pancreatic cancer, in current study we found for the first time that USP33 may serve as an oncogene in PC." (PMID 37322017, 2023).
colon cancer (2 papers, 2021 to 2023). "Among the putative target genes of miR-206 as predicted by miRDB, USP33, which functions in breast, lung, and colon cancer cells, was selected." (PMID 33718387, 2021).
lung adenocarcinoma (2 papers, 2014 to 2018). A carcinoma that arises from the lung and is characterized by the presence of malignant glandular epithelial cells. "In addition, somatic USP33 missense mutations were detected in of other cohorts of lung adenocarcinoma (2.7%–6.2%) and lung squamous cell carcinoma (3.4%) samples." (PMID 24981056, 2014). "We sought to identify the downstream target genes of miR-365a-3p and found that USP33 expression was strongly negatively correlated with that of miR-365a-3p in lung adenocarcinoma tissues." (PMID 29743814, 2018). "Next, qRT-PCR was used to detect the expression of miR-365a-3p and USP33 in tissues derived from 20 cases of lung adenocarcinoma." (PMID 29743814, 2018). "Additionally, it was previously reported that USP33 exhibits low expression in lung adenocarcinoma tissues and cells." (PMID 29743814, 2018). "We identified USP33 as the downstream target of miR-365a-3p and observed a negative correlation between miR-365a-3p and USP33 expression in lung adenocarcinoma patients." (PMID 29743814, 2018).
lymph node metastasis (2 papers, 2015 to 2022). "Reduced USP33 mRNA levels are correlated with increased tumor grade, lymph node metastasis and poor patient survival." (PMID 26348204, 2015).
Parkinson disease (2 papers, 2025). A progressive degenerative disorder of the central nervous system characterized by loss of dopamine producing neurons in the substantia nigra and the presence of Lewy bodies in the substantia nigra and locus coeruleus. "Another notable instance of decreased ubiquitylation in our dataset involves USP33, a deubiquitylase localized to the mitochondrial outer membrane and known to interact with Parkin, an E3 ubiquitin ligase associated with Parkinson’s disease." (PMID 40480969, 2025). "USP33 can directly target parkin RBR E3 ubiquitin protein ligase (PRKN), and knockdown of USP33 enhances PRKN-mediated mitophagy, providing a new therapeutic strategy for the treatment of Parkinson's disease." (PMID 40083330, 2025).
Hypertension (1 paper, 2023). The presence of chronic increased pressure in the systemic arterial system. "USP33, which we found to be associated with early-onset hypertension, encodes a deubiquitinating enzyme implicated in regulating expression of the β2-adrenergic receptor regulation." (PMID 36928819, 2023).
liver cancer (1 paper, 2025). An epithelial or non-epithelial malignant neoplasm that arises from the liver.
neuroblastoma (1 paper, 2023). Neuroblastoma (NB) is the most common solid, extracranial childhood tumor. "USP33-knockdown increased the stability of parkin and its translocation to depolarized mitochondria, which enhanced mitophagy and protection to human neuroblastoma cells against apoptotic cell death induced by the neurotoxin 1-methyl-4-phenyl-1,2,3,6-tetrahydropyridine." (PMID 37874827, 2023).
neuroendocrine tumors (1 paper, 2020). "We propose that compounds that modulate the deubiquitinase activity of either USP33 or STAMBP may be of therapeutic use in the treatment of neuroendocrine tumors that result from impaired GCGR trafficking and signaling." (PMID 32967969, 2020).
retinoblastoma (1 paper, 2022). A malignant tumor that originates in the nuclear layer of the retina. "In retinoblastoma, USP33 was reported to regulate cell proliferation and inhibit apoptosis via stabilizing SP1 and activation of SP1/PI3K/Akt signaling pathway." (PMID 36582601, 2022).
testicular germ cell tumor (1 paper, 2022). A germ cell tumor arising from the testis. "The result showed that all the rest four USPs were aberrantly expressed in several other tumors with USP32 lower expression in testicular germ cell tumors and USP33 higher expression in thymoma." (PMID 36582601, 2022).
viral infection (1 paper, 2024). "Investigating the broader implications of targeting USP33 in other viral infections may offer valuable insights into the development of broad‐spectrum antiviral strategies." (PMID 39301916, 2024). "However, the role of USP33 in viral infection and replication remains largely unknown." (PMID 39301916, 2024). "In contrast to USP39, which showed a slightly up‐regulated expression level after viral infection, we did not see changes in the total protein level of USP33 after viral infection in a variety of cell lines." (PMID 39301916, 2024). "Although the protein level of USP33 is not affected by viral infection, we compared the transcriptomics in severe patients, mild patients, and healthy populations, and found higher levels of USP33 in patients with COVID‐19, which reflected the impact of USP33 on disease severity." (PMID 39301916, 2024).
von Hippel-Lindau disease (1 paper, 2008). An autosomal dominant disorder caused by pathogenic variants in the VHL gene, leading to an increased risk of various benign and malignant tumors, including hemangioblastomas, retinal hemangiomas, endolymphatic sac tumors, renal cell carcinoma, and pheochromocytomas. "UBP33 (encoded by USP33/VDU1) and UBP20 (encoded by USP20/VDU2) are 59% identical USP-type DUBs that interact with the tumor suppressor E3 ubiquitin ligase VHL (pVHL), mutations in which are associated with von Hippel-Lindau disease." (PMID 19007433, 2008).
cancer (15 papers, 2014 to 2026). A tumor composed of atypical neoplastic, often pleomorphic cells that invade other tissues. "We further interrogated the association of USP33 expression with patient survival in other types of cancers." (PMID 24981056, 2014). "Ubiquitin carboxyl-terminal hydrolase 33 (USP33) is an essential deubiquitinase that stabilizes the HIF-2a protein (encoded by the Epas1 gene) via the ERK1/2-dependent mechanism to promote a hypoxia response in cancer cells." (PMID 41009560, 2025). "The de‐ubiquitinase USP33 has been shown to possess either tumour‐promoting or inhibitory effect on human cancer cells." (PMID 39694539, 2025). "The current reported findings in different tissue types of human cancer cell lines show a controversial effect of USP33 on tumorigenicity, suggesting the existence of unidentified molecular mechanism(s) that mediate USP33‐regulated tumorigenic phenotype." (PMID 39694539, 2025). "In this study, it was shown that DHA reduced the expression level of RalB and USP33 in three different types of cancer cells." (PMID 32577124, 2020). "Our study reveals the inhibitory function of Slit‐Robo signalling in GC and uncovers a role of USP33 in suppressing cancer cell migration and EMT by enhancing Slit2‐Robo1 signalling." (PMID 30896071, 2019). "Ubiquitin-specific proteases (USPs) make up the largest family of deubiquitinating enzymes (DUBs), and several USPs, such as USP7 and USP33, have been reported to play roles in regulating cancer development." (PMID 27835898, 2016). "Consistent with our clinical data, USP33 knock-down increased the carcinogenicity of cancer cells, such as up-regulating the EMT protein expression and promoting cell proliferation and invasion." (PMID 27835898, 2016). "However, the mechanisms regulating USP33’s activity toward its substrates in cancer contexts remain largely unexplored." (PMID 40695806, 2025). "However, when the recombinant Slit2 protein is added to cancer cells, Slit2 activates the expression of USP33, a deubiquitinating enzyme, which prevents ROBO from degradation and stabilizes the protein." (PMID 36361532, 2022). "DHA treatment induced autophagy leading to the reduction of RalB/USP33 expression in cancer cells." (PMID 32577124, 2020). "Moreover, studies have shown that USP33-mediated SLIT2/ROBO1 signalling participates in the development of cancer." (PMID 29743814, 2018). "One hypothesis is that during the SDF-1 induced migration of cancer cells, USP33 expression is down-regulated in certain microenvironments, which enhanced cell migration capacity." (PMID 27835898, 2016). "However, current reports illustrate a controversial role of USP33 in human cancer cells." (PMID 39694539, 2025). "In terms of treatment, USPs can be used as cancer therapeutic targets, such as inhibitors of USP1, USP4, USP7, USP9X, and USP33 for prostate cancer, lung cancer, breast cancer, and hematological malignancies, among others." (PMID 38613804, 2024). "Previous studies have connected USPs, such as USP7, USP21, USP22, USP33, USP39, USP54, and others, to carcinogenesis in several cancer types." (PMID 38613804, 2024). "USP33 deubiquitinates and thus maintains the stability of ROBO1, thereby regulating the activity of SLIT2 and inhibiting cancer cell metastasis." (PMID 29743814, 2018). "One of the most important GPCRs in cancer migration and invasion is CXCR4, however, the correlation between CXCR4 and USP33 hasn't been investigated." (PMID 27835898, 2016).
cancer (continued). "Our study not only established USP33 as a novel prognosis biomarker in advanced CRCLM patients, but also highlighted the significance of β-arrestin-dependent ERK signaling in cancer development." (PMID 27835898, 2016). "In addition, USP33 is involved in Slit signaling in inhibiting breast caner cell migration, suggesting that USP33 may play an important role in cancer invasion and metastasis." (PMID 24981056, 2014). "The tumor suppressing role of USP33 is at least partially dependent on β-arrestin-mediated ERK signaling downstream of SDF-1/CXCR4, demonstrating the prospect of deubiquitinating enzyme modulator and biased-ligand development of GPCRs in cancer therapy." (PMID 27835898, 2016). "USP33 could also serve as the deubiquitinating enzyme of HIF-1A protein and promote the stability of HIF-1A protein to control the HIF-1A signaling pathway in cancers." (PMID 37322017, 2023). "However, the regulation of USP33 expression or activity in human cancer is not well understood." (PMID 40695806, 2025).
tumor (12 papers, 2014 to 2025). "Our results showed that USP33 deficiency significantly decreased the tumor growth of subcutaneous xenograft nude mice while the overexpression of TGFBR2 rescued the effect of USP33." (PMID 37322017, 2023). "To further clarify the potential function of USP33 in tumorigenic process, we employed in vitro cell culture and USP33 conditional knockout mouse models to determine the potential significance of USP33 in tumour progression." (PMID 39694539, 2025). "Given the important role of USP33 in regulating the proliferation and invasion of PC cells in vitro, we next verified the function of USP33 on the tumor growth and metastasis of PC in vivo." (PMID 37322017, 2023). "The IHC results of xenografted tumor showed that USP33 depletion inhibited the expression of Ki67, PCNA, TGFBR2 and ZEB1." (PMID 37322017, 2023). "Taking together, our results demonstrated that USP33 promoted the tumor growth and metastasis of PC in a TGFBR2-dependent manner." (PMID 37322017, 2023). "USP33 is a classical mediator of Slit-Robo signaling pathway which is considered to be a tumor suppressor." (PMID 36582601, 2022). "USP33 expression was inversely correlated with tumour size, lymph node metastasis and neural invasion." (PMID 30896071, 2019). "Knock‐down of USP33 in Slit2 expressing GC cells, however, diminished the inhibitory effects of Slit2 on tumour metastasis." (PMID 30896071, 2019). "USP33 is a deubiquitinating enzyme that is closely related to the occurrence and development of tumours." (PMID 29743814, 2018). "Our in vitro and in vivo findings convincingly demonstrate the anti‐tumour effect of USP33." (PMID 39694539, 2025). "Although the expression levels of USP10, USP32, and USP33 were also significantly related to tumor differentiation to some extent, the result may be unreliable due to the small sample size." (PMID 36582601, 2022). "Notably, the promoter methylation levels of USP33 presented prominent positive correlation with tumor differentiation except for grade 4 because of the relatively small sample capacity." (PMID 36582601, 2022). "USP33 has been confirmed to inhibit the development of a variety of tumour cells." (PMID 29743814, 2018). "Besides, the primary CRC tumor stage (P = 0.019), LN metastasis (P < 0.001), and USP33 expression in CRCLM (P < 0.001) were also associated with the disease relapse." (PMID 27835898, 2016). "In addition, pretreatment with dynasore can also attenuate the effects of USP33-siRNA in promoting cell proliferation and invasion, indicating that the USP33's role as a tumor suppressor is at least partially mediated by β-arrestin-dependent ERK signaling." (PMID 27835898, 2016). "Taken together, USP33 expression was down-regulated in tumor tissues." (PMID 27835898, 2016). "The down-regulation of USP33 in clinical specimens indicated that the USP33 may act as a tumor suppressor in the CRC development." (PMID 27835898, 2016). "For instance, USP33 was shown to inhibit cell migration through deubiquitinating and stabilising roundabout homologue 1 (ROBO1), thus functioning as a tumour suppressor in lung cancer cells." (PMID 39694539, 2025). "Our study showed that USP10, USP14, USP18, USP32, USP33, and USP39 (termed as six-USPs) expressions were significantly elevated in tumor tissues." (PMID 36582601, 2022).
tumor (continued). "USP33 low-expression in CRC and CRCLM were both correlated with advanced tumor stage and positive LN metastasis." (PMID 27835898, 2016). "On the other hand, the consistent stimulation of SDF-1 and down-regulation of USP33 gradually promote the degradation of CXCR4, which contribute to the lower CXCR4 level in liver metastases than primary tumor tissues." (PMID 27835898, 2016). "In addition, we evaluated the expression of USP33 on both RNA level and protein level from another 14 paired fresh-frozen tissues, which showed that USP33 expression in tumor tissues was lower than that in adjacent non-tumorous tissues." (PMID 27835898, 2016).